CCNE1 (cyclin E1)
Diseases named in the same sentence as CCNE1 in open-access papers (continued):
Sharing a sentence is not in itself a finding about the gene and the disease.
cancer (continued). "In summary, the current study, to the best of our knowledge, was the first to analyze clinical outcome in patients with various advanced CCNE1 amplification cancers who were referred to a designated phase I trial clinic." (PMID 35610322, 2022). "Oncogenes, such as MET, PLK1 and CCNE1, demonstrated higher expression levels in cancer tissues than in normal tissues in the TMA and TCGA data sets." (PMID 36137139, 2022). "Loose of the cell cycle regulation is central to this oncogenic proliferation, and dysregulation in markers (such as E2F1, PLK1, CCNE1, and CCND1) associated with cell cycle mechanism is one of the most prominent molecular aberrations in all cancers." (PMID 35419294, 2022). "Among most of the descendant cancer cells, more cancer-related changes were obtained, such as in CCNE1, POU2AF1, and KRAS." (PMID 35951662, 2022). "In certain cancers, increased CCNE1 expression (amplification or transcriptional upregulation) deregulates the cell cycle at the G1/S and G2/M checkpoints by accelerating S-phase entry and stimulating premature mitosis." (PMID 35315355, 2022). "In other cancers, increased expression of CCNE1 through transcriptional upregulation or amplification often leads to a deficient G1/S checkpoint, thus enhancing DNA replication stress and genomic instability." (PMID 35315355, 2022). "Cyclins and cyclin-dependent kinases (CDKs) are major effectors of the cell cycle with key role in cancer where our data shows downregulation of key cell-cycle proteins such as cyclin D1 and Geminin and mRNA levels of CCNE1, CCNF, CDK1, CDK2 and CDK5." (PMID 35902556, 2022). "Screening for the impact of other amplified cancer genes in HEK293 cells also demonstrated that EGFR, AKT2, CCND1, CCNE1, SKP2, and FGFR3 caused both increased abundance of phosphorylated ZFP36/TTP and ARE-post-transcriptional reporter activity." (PMID 34535639, 2021). "CCNE1 has been reported to upregulated in various human cancer including breast, bladder and ovarian." (PMID 33827486, 2021). "A pan-cancer analysis based on TCGA and GTEx databases demonstrated CCNE1 was prominently expressed in nearly all human cancers." (PMID 33791304, 2021). "We observed only a moderate positive correlation between cyclin E1 T62 phosphorylation and cyclin E1 expression (r = 0.183, P = 0.009, Spearman), indicating that a proportion of cancers had very low cyclin E1 T62 phosphorylation." (PMID 34465787, 2021). "Bcl-2 and CCNE1 were famous factors contributing to cell proliferation in nearly all kinds of human cancers." (PMID 34660260, 2021). "In this study, we found that high expression of CCNE1 (log2FC > 1, q < 0.01) was presented in 18 of 31 cancer types." (PMID 33613291, 2021). "Overexpression of cyclin E1 increases the proportion of cells in the S phase, which leads to increased Rb phosphorylation and cell proliferation in many cancer cell line models." (PMID 34604242, 2021). "The results of PPI demonstrated that the five TFs were tightly associated with many critical cancer related factors or pathways, such as SMAD4, MMP13, IL-5, IL-2, CYP2E1, CCNE1 and CDH1." (PMID 34405021, 2021). "Many of these RNAs have been extensively studied as cancer-related molecules, such as miR-181a, CCNE1, and WIF1." (PMID 33718161, 2021). "We also observed amplifications of canonical cancer genes, including CCNE1 on 19q12 and MYC on 8q24." (PMID 34145257, 2021). "Among all cyclin genes analyzed, CCNA2, CCNE2, CCNB2, CCNB1, CCNF, and CCNE1 were most elevated in the included cancers." (PMID 33996604, 2021). "The CCNE1 gene, located at chromosome position 19q12, is a frequent site of amplification in cancer." (PMID 34465787, 2021). "We found that high expression (log2FC > 1, q < 0.01) of CCNE1 was presented in 18 of 31 cancer types." (PMID 33613291, 2021).
cancer (continued). "With an increase in CCNE1, cancer cells can further manipulate cell replication by amplifying CCNE1, CDK2, and E2F, entering into a positive feedback loop charging through to the S phase." (PMID 33182737, 2020). "This in turn leads to the expression of cyclin A and cyclin E1, which are essential for cell cycle progression, cancer growth, proliferation and migration." (PMID 32970611, 2020). "Gene amplification and ectopic CCNE1 overexpression induces CIN and is associated with aggressive cancers, chemotherapeutic resistance and poor prognosis." (PMID 32106628, 2020). "These factors, produced by amniotic stem cells, can regulate the expression of cancer cell proteins associated with the cell cycle, such as cyclin-dependent kinases (CDK2, CDK4, CDK6) and cyclins (cyclin D2, cyclin E1, cyclin H)." (PMID 32972410, 2020). "Lastly, CCNE1 amplification was one of the previously reported genes in EC, and we also identified CCNE1 amplification in serous-like cancers of TGCA samples." (PMID 32877461, 2020). "Cyclin E1 is often found to be overexpressed in cancers, specifically in TNBCs and high-grade ovarian cancers, which is accompanied by higher CCNE1 mRNA expression levels in these cancers." (PMID 33028815, 2020). "To further examine the modulatory effects of cyclin E1 on anti-cancer sensitivity, we measured the IC50 of regorafenib and sorafenib after cyclin E1 overexpression." (PMID 31349793, 2019). "Targeting to CDCA4, BCL2L2, YAP1, AKT-3 and Cyclin E1, miR-15a has been found to significantly reduce cancer cell survival and aggressiveness." (PMID 30733644, 2019). "ERBB2, CCND1, CCNE1 are well-characterized oncogenes present among our curated set of cancer driver databases." (PMID 31729402, 2019). "As the key regulator of G1-S transition, CCNE1/2 are also involved in the development of various cancers." (PMID 31455378, 2019). "We first found that silencing of CCNE1 had minute impact on CDK2 level, in reminiscence of a recent report that overexpression and amplification of CCNE1 is dependent on CDK2 activity in Cyclin E1 driven cancer cell lines." (PMID 31313989, 2019). "Some of these integration sites interrupt important cancer genes such as CCNE1 (sample 106 T, chr19:30304177) and NTRK3 (sample 108 T, chr15:88688212)." (PMID 30704462, 2019). "Given that CCNE1 is amplified in a variety of cancers, targeting tumors with this genotype is a hotspot of investigation." (PMID 31313989, 2019). "A panel of eight cancer driver genes (CCNE1, TPX2, ELF3, FANCL, JAK2, GSK3B, CEP76, and SYK) were differentially expressed in recurrent TNBCs, and were also overexpressed in TCGA and METABRIC." (PMID 30665374, 2019). "Remarkably, USP22 knockout had pronounced effects on expression of these important cancer-associated gene sets such as c-Myc, E2F, and selected genes including ALDH1A3, CCNE1/G1, E2F6, HOXA1, MMP9, NFKB2, TP63, TPM4, SET7/9 were validated by qRT–PCR." (PMID 31842906, 2019). "Higher levels of cyclin E1 expression were found in high-grade carcinomas than in low-grade carcinomas." (PMID 31349793, 2019). "Other genes like CCNE1, SENP5, FN1, KMT2B, and DUX4 were alsoidentified by HGT-ID; these genes were previously reported to be associated with tumorigenesis or cancer invasion." (PMID 30016933, 2018). "Blocked NF-κB activity reduced cyclin E1 and cyclin D1 expression, which regulates cell cycles in various cancers through cell-cycle checkpoints, thus inhibiting the passage through the restriction point in late G138." (PMID 29531296, 2018). "CCNE1 presents a 3’ UTR lengthening example in six cancer types (LUAD, BRCA, HNSC, KIRP, LIHC, and LUSC)." (PMID 30005633, 2018).
cancer (continued). "Generally, dysregulation of CCNE1/2 activity is present in various cancers, resulting in disrupted G1–S transition and uncontrolled cell proliferation." (PMID 30012177, 2018). "As well, ATR and CHK1 inhibitors have shown selective cytotoxic effects on Cyclin E1 (CCNE1) overexpressing cancer due to the high dependency of these tumors on the ATR/CHK1 axis." (PMID 30466442, 2018). "Three pathways demonstrated top priorities, and the one with specific associations with cancers, ‘pathways in cancer,’ was analyzed with its four highlighted genes, namely, BIRC5, E2F1, CCNE1, and CDKN2A, which were validated using Oncomine." (PMID 28316892, 2017). "Cancer patients with high CCNE1 expression levels have shown increased sensitivity to CDK2 inhibitors SNS-032." (PMID 28178664, 2017). "Iso-3 induced growth arrest of cancer cells in G0/G1 concomitant with increased p21 and p27 expression and reduced cyclin E1, PCNA and c-myc levels." (PMID 27006469, 2016). "Among analysis, MYC, Argonaute2 (AGO2), Y-box binding protein 1 (YBX1), cyclin E1 (CCNE1) were involved in organismal abnormalities and cancer." (PMID 27463019, 2016). "Similar to other forms of cyclin E1 deregulation, post-transcriptional regulation of cyclin E1 is also disrupted in cancer." (PMID 25830480, 2015). "This is not surprising given that the low molecular weight derivatives of cyclin E1 also has unique binding and function in cancer cells compared to the full length protein." (PMID 25741376, 2015). "Cyclin E1 is overexpressed and present throughout the cancer cell cycle where it advances S phase entry and induces genetic instability." (PMID 25830480, 2015). "Cyclin E1 (or cyclin E) is repressed by miR-15b, miR-16, miR-34c, and miR-145 in other cancer cells." (PMID 25909221, 2015). "Here, we show that miR-497 and miR-34a target the 3′-UTR of CCNE1. miR-497 and miR-34a are downregulated in cancer cells and their ectopic expression inhibited cell proliferation and colony formation in vitro, and inhibited tumor growth in a xenograft model." (PMID 25909221, 2015). "Disruptions in both transcriptional and post-translational regulation result in cyclin E1 overexpression in cancer." (PMID 25830480, 2015). "CCNE1-amplified cancers make up a large subgroup (20%) of HGSOC that lack BRCA mutations and are therefore less likely to respond to PARPi." (PMID 24624361, 2014). "Using the TCGA dataset, we show that cyclin E1-overexpressing, BRCA-wildtype HGSOC have significantly reduced OS compared to BRCA-wildtype cancers with lower cyclin E1 expression." (PMID 24624361, 2014). "In order to select eligible patients, CCNE1-amplified cancers can be easily identified by fluorescence in situ hybridization (FISH)." (PMID 24624361, 2014). "Cyclin D1, cyclin E1 and pRb are known to orchestrate cell cycle progression, and functional interaction between cyclin D1, cyclin E1 and pRb plays an important role in cancer cell growth and tumorigenesis." (PMID 23383003, 2013). "CCNE1 siRNA-mediated silencing, however, was found to reduce the sensitivity of cancer cells to doxorubicin, cisplatin and paclitaxel in cancer cells harbouring 19q12 amplification cells but not in cancer cells lacking amplification of this locus." (PMID 22433433, 2012). "On the other hand, in cancer cells harbouring 19q12 amplification, CCNE1 silencing resulted in a significant decrease in the fraction of cells in S/G2 and increase in the proportion of cells in G1 and subG1 cell cycle phases (P < 0.0001, Chi-square test)." (PMID 22433433, 2012).
cancer (continued). "CDK2 siRNA silencing and inhibition of CDK2 kinase activity using a CDK1, CDK2 and CDK9 inhibitor (AZD5438) resulted in significantly higher reduction in survival of cancer cells harbouring CCNE1 gene amplification." (PMID 22433433, 2012). "siRNA-mediated CDK2 silencing resulted in a significantly higher reduction in cell survival of cancer cells harbouring CCNE1 gene amplification than in cancer cells devoid of amplification of this gene (t-test, P < 0.05)." (PMID 22433433, 2012). "siRNA silencing of all genes mapping to the 19q12 amplicon revealed the existence of genes other than CCNE1 whose expression is selectively required for the survival of cancer cells harbouring amplification of this locus." (PMID 22433433, 2012). "Here we have demonstrated that CCNE1 is a driver of the 19q12 amplicon and that cancer cells harbouring CCNE1 gene amplification display an increased sensitivity to CDK2 RNAi-mediated silencing and chemical inhibition." (PMID 22433433, 2012). "Cancer cells with CCNE1 amplification were shown to be dependent on CDK2 expression and kinase activity for their survival." (PMID 22433433, 2012). "Given known roles of Cyclin E1 in cancer, including de-regulation of the cell cycle and promoting genomic instability, it was the likely driver of the 19q12 locus, however other genes had not been excluded." (PMID 21103391, 2010). "Furthermore, it has been demonstrated in pre-clinical cancer models that PKMYT1 inhibition is a promising strategy for treating CCNE1-amplificated cancers." (PMID 41376855, 2026). "HBV integration frequently targets cancer-associated genes like human telomerase gene (TERT), the lysin methyltransferase 2B (KMT2B), cyclin E1 (CCNE1), and cyclin A2 (CCNA2), fragile genomic sites, and repetitive sequences, enhancing HCC risk (26, 27, 33, –, 37)." (PMID 40699151, 2025). "The formation mechanisms and functions of LMW-cyclin E1 vary across different cancer types." (PMID 40959067, 2025). "Some drivers, such as CCNE1, are well-established cancer drivers." (PMID 38721669, 2024). "Furthermore, AM-1882 is active in a subset of cancer cell lines with CCNE1, BRCA1 and RB1 gene alterations and can enhance apoptosis when combined with PARP inhibition." (PMID 38151625, 2024). "In conclusion, CCNE1 amplification may effectively predict the occurrence of adverse prognostic events in cancer patients, and the control of CCNE1 amplification will become a hot research direction for the control of adverse prognostic events." (PMID 39591374, 2024). "However, a significant subset of HRP HGSC lack CCNE1 amplification, and the molecular drivers of these cancers are still being defined." (PMID 38894867, 2024). "Whether this is true in CCNE1-amplified cancers, which might be highly CDK2-dependent, remains unclear." (PMID 38047585, 2024). "Recent studies have confirmed that PKMYT1 inhibitors may be an effective approach for the treatment of CCNE1-amplified cancers." (PMID 39591374, 2024). "For instance, cancers with high CCNE1 expression may exhibit resistance to certain chemotherapeutic agents that target cell cycle pathways." (PMID 39591374, 2024). "In addition to RNAi, small molecule inhibitors like Adavosertib, a WEE1 inhibitor, have been explored for their ability to inhibit cyclin E/CDK2 complexes, slowing down cell cycle progression in cancers with CCNE1 amplification." (PMID 39591374, 2024). "Modulation of CCNE1 expression in HER2-positive cancer cell lines regulated sensitivity to the HER2-targeting antibody–drug conjugate trastuzumab deruxtecan (T-DXd) in vitro, and adavosertib acted synergistically with T-DXd in HER2-expressing patient-derived xenografts in vivo." (PMID 38717153, 2024). "Moreover, their insensitivity to CDK4/6i indicates the primacy of CDK2 in driving the G1 to S transition in CCNE1-amplified cancer cells." (PMID 38047585, 2024). "Similarly, the cyclin genes CCNA2 and CCNE1 are higher in precancer and cancer than controls (p < 0.0001, p < 0.0001)." (PMID 39672307, 2024).
cancer (continued). "The impacts of CCNE1 on the immunotherapy sensitivity of cancer patients were then evaluated." (PMID 36964635, 2023). "We explored the association between the expression levels of CCNE1 and TMB, MSI, or neoantigen to investigate whether CCNE1 acts as an indicator of immunotherapeutic responses across cancers." (PMID 36964635, 2023). "A similar mechanism may be apparent in cancer cell lines that grow despite the constant replication stress imposed by high cyclin E1 levels." (PMID 37519629, 2023). "It remains to be seen whether redundancies in the CDK2/CCNE1 pathway (CDK1 for CDK2, CCNE2 for CCNE1) observed in normal cells pose another challenge of targeting this pathway in cancers." (PMID 36572991, 2023). "Therefore, bioinformatics analyses of pan-cancer datasets were carried out to explore how CCNE1 regulates tumorigenesis." (PMID 36964635, 2023). "It has also been reported to induce chromosome instability via cyclin E1 in other cancers." (PMID 37892181, 2023). "Cyclin D1 and Cyclin E1 expressions were compared for impact on survival for gastric cancer, and it was observed that Cyclin E-negative cancers portrayed good outcomes, while Cyclin E-positive cancers showed worse outcomes, as indicated through survival curves." (PMID 36769170, 2023). "Indeed, targeting CCNE1-high cancers with inhibitors of the ATR signaling pathway is a well-studied strategy." (PMID 38032106, 2023). "Our study demonstrated that CCNE1 is upregulated in multiple cancers in the TCGA database and may be a promising predictive biomarker for the immunotherapy response in some types of cancers." (PMID 36964635, 2023). "Based on these findings, it appears that methylation of the CCNE1 promoter may influence its expression in a variety of cancers." (PMID 36964635, 2023). "In addition, the relationship between CCNE1 gene alteration status and prognosis in various cancers was explored via cBioPortal analysis of the TCGA dataset." (PMID 36964635, 2023). "Numerous studies have reported that m6A modification plays a crucial role in numerous types of cancer, so we explored whether CCNE1 is affected via m6A modification." (PMID 36964635, 2023). "Indeed, cancer cells generally display elevated replication stress due to activated drivers such as CCNE1, KRAS and MYC." (PMID 37325550, 2023). "Overactivation of CDK2 activity may limit the potency of CDK4/6 inhibitors, and individual cancer cells with high cyclin E1 levels may increase CDK2 activity thus bypassing CDK4/6 blockade." (PMID 37369022, 2023). "We conclude that PKMYT1 inhibition is a promising therapeutic strategy for CCNE1-amplified cancers." (PMID 35444283, 2022). "Similarly, SKP2 targets Cyclin E1, whose aberrant accumulation leads to cell cycle and apoptotic defects that also promote cancer development and progression." (PMID 36496990, 2022). "Thus, CCNE1 mRNA expression is a patient selection biomarker for WEE1 inhibitor response in patients with cancer at the clinical level." (PMID 35315355, 2022). "Moreover, SKP2 has established proteolytic targets such as P27 and Cyclin E1, which are oncogenes frequently amplified at the level of the genome in many cancers, including ~20% and ~23% of CRC cases, respectively." (PMID 36496990, 2022). "HGSC is copy-number driven cancer in which CCNE1 amplification frequency is 15–20%22." (PMID 35169222, 2022). "Many cancer-related molecules are included in this network, such as miR-181a, CCNE1, and WIF1." (PMID 33718161, 2021). "Since the cyclin E1 degradation machinery was deregulated in BRCA1 mutant cancers across our cohort, we investigated whether cyclin E1 turnover is dysregulated in cell lines with mutant BRCA1 or BRCA1 loss." (PMID 34465787, 2021). "Thus, it is the collective lack of Cyclin E1 turnover arising from defects in the expression and/or function of SCF complex members that is expected to phenocopy genomic amplification of CCNE1 and contribute to cancer pathogenesis." (PMID 35008511, 2021).